FASLG (Fas ligand)
Diseases named in the same sentence as FASLG in open-access papers (continued):
Sharing a sentence is not in itself a finding about the gene and the disease.
cancer (continued). "To the best of our knowledge, we noticed for the first time that conditioned medium from NK-92 cells, which contains IFNγ, can sensitize cancer cells to apoptosis triggered by FASLG." (PMID 40512405, 2025). "NK-Exos were found to contain perforin and killer proteins (i.e., Fas ligand (FasL)) that inhibit cancer growth." (PMID 39539445, 2024). "If this is the case, treatment with ActD + Nut3a can change FASLG from a promoter of cancer growth to its inhibitor." (PMID 39068622, 2024). "Unexpectedly, some cancer cells depend on the constitutive activity of FAS, stimulated by cancer-produced FASLG, for optimal growth." (PMID 39068622, 2024). "TAMs also induce matrix metalloproteinase (MMP) expression, resulting in the cleavage of the Fas ligand from cancer cells." (PMID 39796695, 2024). "For instance, neutrophils with enhanced expression of tumor necrosis factor-related apoptosis-inducing ligand (TRAIL) and Fas ligand (FasL) induce apoptosis through direct contact with cancer cells." (PMID 38760815, 2024). "MMPs and ADAM, especially MMP-7 and ADAM10, provide apoptotic signals to cancer cells by removing the Fas ligand, a transmembrane receptor Fas, on the cell surface." (PMID 38956273, 2024). "In this report, we demonstrated that actinomycin D and nutlin-3a cooperate to sensitize cancer cells to apoptosis induced by FASLG." (PMID 39068622, 2024). "NK cells and CD8 + T lymphocytes can also induce apoptosis in cancer cells by releasing Fas ligand (FasL), tumor necrosis factor (TNF)-α and interferon (IFN)-γ." (PMID 37221555, 2023). "Fas and Fas ligand (FasL/CD95L) are the two most important apoptosis-inducing molecules in cancer cells." (PMID 38298540, 2023). "For instance, FADD, FASLG, RIPK1, RIPK3, and TNF were more prone to copy number gain than loss in pan-cancer, but FAS and TLR3 displayed the reverse tendency." (PMID 37351504, 2023). "These cells are loaded with direct cytotoxic mediators, including granzymes, perforin, interferon gamma (IFNγ), and Fas Ligand, that allow them to serially kill cancer cells displaying cognate antigens within only few minutes of interaction." (PMID 37081897, 2023). "In summary, we have shown for the first time that PIP increases the sensitivity of BC cells to apoptosis induced by anti-cancer drugs, which is associated with overexpression of specific pro-apoptotic genes (CRADD, DAPK1, FASLG, CD40, and BNIP2)." (PMID 37085653, 2023). "CTLs can kill cancer cells via Fas ligand (FasL)-mediated apoptosis and perforin/granzyme-mediated granule-exocytosis mechanisms." (PMID 36726985, 2022). "To promote the clinical transformation of the NRGs signature, we further identified the sensitive FDA-approved drugs for multiple cancer cell types with higher expressions of FASLG, TLR3, and ZBP1." (PMID 35165523, 2022). "TCMNPs can not only target tumors through T-cell membrane-initiating proteins and kill cancer cells by releasing anticancer molecules and inducing Fas ligand-mediated apoptosis, but also resist cancer by eliminating TGF-β1 and PD-L1." (PMID 36005653, 2022). "Cancer cells also kill aggressive lymphocytes by expressing cell surface molecules that induce apoptosis, such as Fas ligand (FasL)." (PMID 36313280, 2022). "Measurements of serum expression levels in cancer patients undergoing cisplatin treatment have earlier been explored for four of these inflammatory proteins, namely, FASLG, CXCL5, CD5, and IL-12." (PMID 35682983, 2022).
cancer (continued). "In the “activated” state, CTL can induce target cancer cells killing through granule cytokinesis and Fas ligand (FasL)-mediated apoptosis." (PMID 36159787, 2022). "Epithelial mesenchymal transition (EMT) and stiffness make cancer cells more aggressive by excessive production and secretion of FASLG." (PMID 36009404, 2022). "Cancer cells with higher FASLG expression were more sensitive to LEE-011, oxaliplatin, and palbociclib." (PMID 35165523, 2022). "One major function of CD8+ T cell destruction of targeted cancer cells is via Fas and Fas Ligand (Fas/FasL) interaction." (PMID 36290817, 2022). "The signaling pathway in which FASLG is active has a role in the apoptotic response of damaged cells, such as cancer cells." (PMID 36359256, 2022). "Focusing on these mechanisms, in cultured cells of hepatocytes, resveratrol induces cancer cell death by modulating various transduction pathways through the regulation of Fas and Fas-ligand (FasL) levels." (PMID 33805795, 2021). "MANOVA on these genes reveals that this combined set of 7 genes (MYC, CD40LG, CCL4, IL7, TCF4, CCR7 and FASLG) is together statistically significantly reliant on both time post-exposure (p = 0.042) and cancer type (p < 0.001)." (PMID 33941218, 2021). "Fas ligand/receptor signaling plays critical roles in the regulation of the immune system and cancer progression." (PMID 32545773, 2020). "The apoptosis inducer Fas ligand (FasL) is expressed in the vasculature of different types of cancers such as breast, ovarian, bladder, colon, and prostate cancer, but not in the normal vasculature." (PMID 32754274, 2020). "These would recognise the cancer cell by binding its FAS receptor to the FASLG expressed on their membrane and hence induce apoptosis in a cancer cell." (PMID 32606315, 2020). "Fas and Fas ligand (FasL /CD95L) are considered to be the most important apoptosis-inducing molecules in various cancer cells." (PMID 32582642, 2020). "Stromal fibroblasts so called CAFs suppress CD8+ cells function via PDL2 and FAS-ligand, and enhance secretion of interleukin (IL)-6 via crosstalk with cancer cells resulting decreasing accumulation of CD8+ cells." (PMID 33081727, 2020). "More studies in larger patient cohorts are needed to fully understand the FAS and FASLG pathways and their possible role in cancer progression or suppression." (PMID 32606315, 2020). "Extracellular PAI-1 inhibits the cleavage of Fas Ligand (FasL) by plasmin at the surface of cancer cells protecting them from FasL-mediated apoptosis and chemotherapy induced cell death." (PMID 32867190, 2020). "It was shown that type II transmembrane protein, Fas ligand (FasL), present in the structure of exosomes released from cancer cells, stimulates T cell apoptosis and is cytotoxic to natural killer (NK) cells." (PMID 32537468, 2020). "The resulting antitumor activity was mediated by the Fas/Fas ligand axis, the granzyme/perforin axis, and the release of cytokines that sensitized the cancer stroma." (PMID 31804974, 2019). "In colon-cancer cells for example, a Fas (expressed on mesothelial cell)- Fas ligand (expressed on cancer cells) mediated mechanism of killing mesothelial cells has been described." (PMID 30200478, 2018). "The production and release of exosomes bearing factors capable of inducing apoptosis of the surrounding immune cells, such as Fas ligand (FasL) and galectin 9, is one of the mechanisms used by cancer cells to induce immunosuppression." (PMID 29696022, 2018). "The matrix metalloproteinase (MMPs) is a family of enzymes, bearing the capability to cleave extracellular matrix substrates, as well as promotes the release of pro-TNF-α, Fas ligand, and some cytokines in various cancers cells." (PMID 30428899, 2018). "FasR/Fas ligand (CD95) is one of the most important apoptotic pathway used by immune cells to avoid cancer development." (PMID 28609459, 2017).
cancer (continued). "Fas ligand/receptor interactions play an important role in the regulation of the immune system and the progression of cancer, including OSCC." (PMID 28789700, 2017). "It is possible that miR-181a and miR-21 can suppress the Fas-ligand in cancers as they are shown to interact with the Fas-ligand in bone marrow-derived mesenchymal cells and cardiomyocytes, respectively." (PMID 29164055, 2017). "Both apoptotic and antiapoptotic actions of MMPs are also known; for example, the antiapoptotic signals are transduced to cancer cells by MMP-7's ability to cleave Fas ligand, a transmembrane stimulator of the death receptor Fas, from the cell surface." (PMID 24578639, 2014). "Hematological cancer cells are commonly resistant to Fas ligand (FasL)-induced apoptosis despite normal expression of the Fas receptor." (PMID 25304249, 2014). "Many cancers coincide with notable amounts of Fas Ligand (FasL), which is correlated with poor prognosis." (PMID 24460816, 2014). "Streptochlorin induces apoptosis in human leukemic U937 cancer cells by a dose- and time-dependent manner by modulation of the Fas/Fas ligand (FasL) system, downregulating anti-apoptotic Bcl-2 expression and upregulating pro-apoptotic protein Bax." (PMID 23348928, 2013). "Some of the upregulated genes are related to CSC/’cancer stemness’ such as CXCR4, CD133, EPCAM and SOX9, while others are associated with apoptosis (FASLG, TJP2, DUSP4), the MAPK pathway (MAP2K4, DUSP4), and chemoresistance (MMP1, an ETS1 target gene)." (PMID 24069258, 2013). "αB-crystallin inhibits apoptosis in response to different anti-cancer agents, such as DNA-damaging drugs, TNFα and Fas ligand and has been shown to be a predictor of resistance to chemotherapy." (PMID 23506259, 2013). "In the extrinsic pathway, anthocyanins modulate the expression of Fas and FasL (Fas ligand) in cancer cells, that activates caspase-8, then cleaves Bid to tBid, and ultimately stimulates cytochrome c release." (PMID 28239123, 2013). "Exosomes from various cancer cells were shown to expose Fas ligand (FasL, CD95L) of the death receptor Fas (CD95), which induces T-cell apoptosis and attenuates the function of adaptive immune cells." (PMID 24009895, 2013). "MMP-7 is able to release membrane-bound Fas ligand (FasL), which induces apoptosis of neighboring cells or decreases cancer cell apoptosis, depending on the system." (PMID 22852097, 2012). "Upon activation, CTLs express on their surface the death activator designated Fas ligand (FasL) and the engagement of Fas/FasL pathway lead to mediated apoptosis of cancer cells." (PMID 22190975, 2011). "Many cancers express Fas ligand (FasL/CD95L) in vivo, and can kill lymphoid cells by Fas-mediated apoptosis in vitro." (PMID 14520470, 2003). "Various reports have shown that down-regulation of Fas receptor or Fas ligand expression occurs in some cancer cells." (PMID 12402161, 2002). "Fas-ligand mRNA translation or post-translational processing seems to be regulated differentially in the cancer cell lines depending on malignant transformation." (PMID 11355943, 2001). "Fas ligand (FasL) regulates immunotherapeutic cancer-cell death." (PMID 40593750, 2025). "To test our hypothesis, we pre-exposed cancer cell lines to this drug combination for 45 h and then treated them with recombinant FASLG." (PMID 39068622, 2024). "On the other hand, statins upregulate Fas-ligands (FasL) on the surface of cancer cells." (PMID 39478996, 2024). "Many types of exosomes derived by cancer cells may present the Fas ligand (FasL), whose activation is not only known from the literature to silence the immune response by inducing apoptosis of activated CD8+ T cells, but is also correlated with poor prognosis." (PMID 38391950, 2024). "Additionally, they can initiate the death of cancer cells by activating certain pathways through binding to death receptors with their ligands, such as Fas ligand (FasL)." (PMID 39155358, 2024).
cancer (continued). "Additional studies have shown that MUC1 overexpression by cancer cells is associated with protection from natural killer cells (NK cells), cytotoxic T cell-mediated lysis, and TRAIL- and Fas ligand-induced apoptosis, suggesting that MUC1 contributes to immune evasion in aggressive cancer." (PMID 38540735, 2024). "Cancer cells are generally resistant to apoptosis triggered by FASLG." (PMID 39068622, 2024). "The microenvironment of some cancers appears to be permeated with a high level of FASLG." (PMID 39068622, 2024). "Additionally, T cells can induce apoptosis in cancer cells through interactions involving death receptors and ligands, such as Fas ligands (FasL) binding to Fas receptor on the surface of cancer cells." (PMID 38881904, 2024). "The high expression of soluble FASLG may therefore be a sign of an active immune system, and thus a positive predictor of anti-cancer response." (PMID 38067332, 2023). "FASLG strongly associates with multiple immune checkpoints in SKCM and multiple human cancers." (PMID 36588164, 2023). "In addition, ionized cancer cells exhibit increased expression of the Fas ligand (CD178) and, additionally, the tumor necrosis factor-related apoptotic-inducing ligand (TRAIL) receptor." (PMID 37626666, 2023). "Previous reports have revealed that FASLG is important for tumorigenesis and cancer progression." (PMID 36505472, 2022). "LMP1 can also promote cell survival through upregulation of anti-apoptotic proteins including Bcl-2 and A20 to protect infected cancer cells from potentially cytotoxic signals such as Fas ligand (FasL), TNF-related apoptosis-inducing ligand (TRAIL) mediated by cytotoxic T cells." (PMID 33718235, 2021). "In the brain, cancer cells encounter reactive astrocytes that produce PA, leading to the production of plasmin, which induces carcinoma cell death through the production of the soluble Fas ligand from astrocytes and Fas-expressing cancer cells." (PMID 33669052, 2021). "Additionally, EVs carrying inhibitory ligands, such FasL, interfere with the Fas/Fas-ligand pathway and induce apoptosis of activated T cells following cancer vaccines or adoptive T or NK cell therapy." (PMID 33260606, 2020). "Moreover, MMP-7, an enzyme involved in the cleavage of the Fas ligand, has been shown to play a significant role in various pathological processes, including cancer metastasis, fibrosis, and more." (PMID 32053892, 2020). "In addition, MMP-7 is one of the main regulatory enzymes involved inapoptosis by releases the Fas ligand (FasL) from the membrane then induces apoptosisof neighboring cells, or decreases cancer-cell apoptosis." (PMID 31644669, 2019). "Previously published studies demonstrated that GSK-3 inhibition could lead to upregulation of Fas ligand in cancer cells which could potentially enhance the sensitivity of cancer cells to cytotoxic effects of human immune cells." (PMID 31882719, 2019). "Cancer-derived exosomes could induce T cell suppression by delivering Fas ligand (FasL), PD-L1, TGF-β, adenosine and galectin-9." (PMID 31686989, 2019). "Lymphocytopenia may be due to the apoptosis of lymphocytes drawn by cancer cells using the Fas/Fas-ligand pathway or through an alteration of the hemostasis of lymphocytes." (PMID 30048474, 2018). "In addition, the generation of plasmin from neuron-derived plasminogen by astrocyte that cleaves Fas ligand (FasL) will target the cancer cell and thereby induce a paracrine death signal in cancer cells." (PMID 29641478, 2018). "Furthermore, Fas ligand-positive exosomes derived from cancer cells from a patient with oral cancer results in apoptosis of activated T cells (Taylor and Gerçel-Taylor, 2005), a finding which suggests exosomes have a role in T cell apoptosis." (PMID 28659795, 2017).
cancer (continued). "FASLG/FAS signaling could induce apoptosis in various cancers." (PMID 35754839, 2022). "Cancer cells may further increase their resistance to cytotoxic T cell (CTL) attacks by increasing the expression of cell surface molecules such as Fas-ligand (Fas-L/APO-1-L/CD178)." (PMID 32225076, 2020). "Alteration of FASLG pathway regulating cell death may lead to cancer development." (PMID 29364829, 2018). "KIRC also shows the highest level of T-cell exhaustion, indicated by increased activity of immune checkpoint molecules like FASLG, CTLA4, PDL1, PD1, LAG3, and TIM3, which are involved in immune suppression in cancer." (PMID 40649942, 2025). "It is known that immune cells, particularly T cells, use the Fas ligand (FasL or CD95L) and TRAIL (TNF-related apoptosis-inducing ligand) to activate apoptosis in cancer cells." (PMID 38732110, 2024). "Its soluble form can neutralize the biological functions of three members of the tumour necrosis factor superfamily (TNFSF): Fas ligand (FasL), LIGHT, and TL1A, which is a direct predictor of inflammatory disease progression and cancer metastasis." (PMID 39184952, 2024). "Cancer cells paradoxically express both the Fas (CD95) death receptor and Fas ligand (FasL), yet often exhibit resistance to Fas-mediated apoptosis." (PMID 39092762, 2024). "The expression levels of FASLG and FADD in almost all cancer types were higher than those in normal tissues, and FAS was downregulated in most types of cancer." (PMID 36583248, 2023). "The results showed that MLKL had a strong positive correlation with CASP8, ZBP1, FASLG, RIPK1, and RIPK3 in all 33 cancer types, and RIPK3 was also strongly correlated with CASP8, MLKL, and ZBP1." (PMID 37000317, 2023). "NK cells can also prompt extrinsic apoptosis through the interaction of Tumor Necrosis Factor-Related Apoptosis-Inducing Ligand (TRAIL) and Fas Ligand (FasL) with Death Receptors (Fas, DR4/DR5) on the cancer cell surface." (PMID 38071322, 2023). "Our findings showed that many important necroptosis molecules in the pan-cancer, including PLK1, MLKL, FASLG, and ZBP1, demonstrated a high level of activation in the apoptosis signaling pathway." (PMID 37000317, 2023). "In the Fas-FasL pathway, CD8+ T cells can secrete vesicles containing the Fas ligand (FasL) that bind to the Fas molecule on cancer cells, activating intracellular caspase 8 and inducing cell apoptosis." (PMID 38066642, 2023). "The function of 6 NRGs in our signature, including FASLG, IPMK, FLT3, SLC39A7, HSP90AA1, and LEF1, are studied in various cancer types, including BC." (PMID 35864548, 2022). "Of these DEGs, 6 (EGFR, GATA3, DIABLO, CFLAR, RIPK3, and MAPK8) were repressed, while (ZBP1, PLK1, SPATA2, BCL2, ALK, FASLG, TNFRSF21, and LEF1) were upregulated in cancer cases." (PMID 35610275, 2022). "In comparison, FADD in 12 cancer types, FASLG in 3 cancer types, RIPK1 in 19 cancer types, TLR3 in 25 cancer types, TNF in 11 cancer types, FAS in 22 cancer types, MLKL in 15 cancer types, and RIPK3 in 12 cancer types had homozygous deletions." (PMID 35748782, 2022). "Activated NK cells overexpress CD69, Fas ligand, and TRAIL on their surface, and secrete perforin and granzyme B to kill cancer cells." (PMID 34638944, 2021). "As in the activated state, CTLs kill target cells through granule exocytosis and Fas ligand (FasL)—mediated apoptosis induction, and secrete interferon-α (IFN-α) and tumor necrosis factor-γ (TNF-γ) to induce cancer cell cytotoxicity." (PMID 34663825, 2021).